GLS (glutaminase)
Diseases named in the same sentence as GLS in open-access papers (continued):
Sharing a sentence is not in itself a finding about the gene and the disease.
breast carcinoma (continued). "GLS is highly expressed in certain cancer cells, such as AML, GBM, breast cancer (luminal), lung cancer and pancreatic ductal adenocarcinoma (PDAC), where it provides glutamine required by tumor cells and promotes tumor cell growth and proliferation, but GLS is lowly expressed in BC (basal)." (PMID 39482784, 2024). "We evaluated GLS2 and GLS expression levels in additional cell lines and found that GLS2 expression was reduced in mesenchymal breast cancer cell lines (e.g., SUM159, MDA231, and MDA 468) relative to the epithelial breast cancer cell line (MCF7) and that GLS expression was enhanced." (PMID 31652551, 2019). "Instead, glutaminase (GLS) inhibitors, including bis-2-(5-phenylacetamido-1,2,4- thiadiazol-2-yl) ethyl sulfide (BPTES), CB-839, and compound 968, can alter the acetylation of histones H4 and H3 and downregulate the expression of many tumor-related genes in breast cancer." (PMID 31366176, 2019). "In ER+ breast cancer cells with an aromatase inhibitor resistant phenotype, MYC expression is upregulated by the cross-talk between ER and HER2 and Faslodex inhibited MYC, glutamine transporter solute carrier family (SLC) 1A5, glutaminase (GLS), and glutamine consumption." (PMID 28696357, 2017). "Firstly, as the most frequently used glutaminase inhibitors such as BPTES and CB-839 are GLS1 selective, the resistance to glutaminase inhibition may be due to the differential expression of GLS1 and GLS2 in cells, as demonstrated in luminal and basal-like breast cancer cells." (PMID 33194749, 2020). "Interestingly, although glutamine metabolism is independent of estrogen in aromatase inhibitor-resistant breast cancer, the cross-talk between ER and HER2 upregulates the c-MYC pathway and further increases the expression level of GLS, SLC1A5, and glutamine consumption." (PMID 36077501, 2022).
glioma (71 papers, 2009 to 2025). A benign or malignant brain and spinal cord tumor that arises from glial cells (astrocytes, oligodendrocytes, ependymal cells). "In conclusion, by “sponging” miR‐126‐5p, the lncRNA HOTAIR functions as a ceRNA, causing glioma cells to change their glutamine metabolism and upregulate the expression of GLS." (PMID 40567251, 2025). "Previously, LIPT2 expression has been associated with bad prognosis in glioma, and GLS is recognized as a factor associated with malignant proliferation and invasion in gliomas." (PMID 39913607, 2025). "(2018) reported the regulation function of HOTAIR on glutaminase (GLS) expression through sponging miR-126-5p in a competing endogenous RNA axis HOTAIR/miR-126-5p/GLS that is implicated in glioma progression." (PMID 35912242, 2022). "Further analysis showed that the GLS gene is also involved in the cuproptosis process, tumour mutation, and immune escape in glioma cells." (PMID 36158220, 2022). "Another important finding of this study is that the GLS gene related to cuproptosis is also involved in tumour immunity and tumour mutation of glioma cells." (PMID 36158220, 2022). "Inhibition of glutamine utilization via glutaminase inhibition has also been proposed for treatment of gliomas and NF1-deficient tumor cells." (PMID 29662612, 2018). "This enzyme mitigates the metabolic vulnerabilities associated with IDH mutations and IDH mutated glioma cells demonstrate increased sensitivity to glutaminase inhibition confirming the role of glutaminolysis as a key compensatory pathway in metabolic homoeostasis maintenance." (PMID 40949165, 2025). "The authors hypothesized that glutaminase activity and its close association with immune cells and glucose metabolism may mediate cuproptosis in gliomas in a previously unknown manner." (PMID 39062119, 2024). "Therefore, IDH-mutant glioma cells are thought to be more dependent on GLS, whose inhibition leads to glutamate deficiency." (PMID 34356864, 2021). "Specifically, the abundance of glutamine in glioma further accelerates the tumor anabolism as glutamate converted from glutamine by glutaminase may be metabolized to D2HG in IDH1 mutated glioma cells accompanied by a loss of proper enzymatic activity." (PMID 34490096, 2021). "In addition, IDH-mutated glioma cells are susceptible to the inhibition of glutaminase." (PMID 37296846, 2023). "Through the miR‐126/GLS pathway, the lncRNA HOTAIR modulates GLS expression, ultimately impacting the glutamine metabolism process in gliomas and promoting tumor growth." (PMID 40567251, 2025). "Glioma cells often release large amounts of glutamate through glutaminase, which converts glutamine to glutamate, coupled with potential impairment in extracellular glutamate removal." (PMID 39227460, 2024). "As a competitive endogenous RNA of miR-126-5p, upregulated HOTAIR led to decreasing expression of glutaminase (GLS), thereby inhibiting glutamine metabolism and enhancing the malignancy of glioma." (PMID 39539540, 2024). "(R)-2HG inhibits 2OG-dependent branched chain transaminases BCAT1/2 in IDH-mutant gliomas, creating a dependency on glutaminase to maintain glutathione pools." (PMID 39025958, 2024). "Its regulatory influence on synaptic plasticity and glioma progression inhibition through GLS-mediated glutamine hydrolysis has been well-documented." (PMID 38365684, 2024). "Glutaminase produces a large amount of glutamate in glioma cells, which converts glutamate from glutamine and increases intracellular Ca2+ through P2 × 7Rs." (PMID 37370767, 2023). "Further, another drug called Zaprinast was able to block glutaminase and reduce the proliferation of IDH-mutated glioma cells." (PMID 37296846, 2023). "Targeting glutaminase was also confirmed to be an effective means of inhibiting the growth of IDH1 mutant glioma cells." (PMID 36970537, 2023).
glioma (continued). "A phase I clinical trial (NCT03528642) for IDH mut glioma testing with CB-839 (Telaglenastat) a GLS inhibitor showed that Telaglenastat decreases the intracellular Glu and GSH levels in glioma cells and increases the radiotherapy efficacy in vivo." (PMID 38139462, 2023). "D-2-hydroxyglutarate was also reported to inhibit the branched-chain amino acid aminotransferase (BCAT) transaminases and thus rendered gliomas cells addicted to glutamine and more sensitive to glutaminase inhibition." (PMID 35912242, 2022). "This suggests that GLS has a great relationship with the immune and glucose metabolic processes of glioma cells and is involved in mediating the cuproptosis process of glioma cells." (PMID 36158220, 2022). "We found that only the expression level of GLS was significantly decreased in gliomas (compared to normal tissues); the levels of all other CRGs increased significantly." (PMID 36579333, 2022). "It is reported that inhibition of glutaminase sensitizes the IDHmut glioma cells to oxidative stress in vitro and to radiation in vitro and in vivo, suggesting an effective role of this inhibition against IDHmut gliomas." (PMID 35409380, 2022). "We performed cell growth, cell cycle, and protein expression in glutamine deprived or Glutaminase (GLS) gene silenced glioma cells." (PMID 33681764, 2021). "Treatment with GLS inhibitors showed a greater reduction in viability for mutIDH1 compared with WT IDH1 glioma and AML cells." (PMID 35028610, 2021). "The proper function of glutaminase would be an important factor between the IDH1/2 mutational status and the WHO grade classification of gliomas." (PMID 34490096, 2021). "We analyzed polar metabolites in sensitive (ENO1-deleted) and resistant (ENO1-WT) glioma cells treated with enolase and glutaminase inhibitors." (PMID 34172075, 2021). "Glu was also identified in pediatric low-grade glioma using an LC-MS approach, wherein everolimus treatment resulted in glutaminase inhibition, which in turn led to reduced Glu levels, as well as result of extracellular metabolome study of U87-MG cell line." (PMID 34068300, 2021). "While in glioma, GLS was confirmed to be the direct target of miR-126-5p, and miR-126-5p significantly reduced the expression of GLS in mRNA and protein levels." (PMID 33849550, 2021). "LncRNA HOTAIR regulated the expression of GLS through the miR-126/GLS pathway, thus changing the glutamine metabolism process of glioma and promoting the development of the tumor." (PMID 33849550, 2021). "Glutamine deprivation and GLS gene silencing reduced glioma cell proliferation in vitro in glioma cells." (PMID 33681764, 2021). "We also determined the synergy between enolase inhibitors and the glutaminase inhibitor CB-839 in glioma cells in vitro and in vivo in both intracranial and subcutaneous tumor models." (PMID 34172075, 2021). "To further prove that SNAP25 inhibited glioma progression through activating GLS, we applied GLS-shRNA to rescue the SNAP25 overexpressed cells." (PMID 34490096, 2021). "Glutamine metabolism importance is underscored by the robust efficacy afforded by (glutaminase) GLS inhibitors/glutamine antagonist in preclinical cancer studies and a recent phase I clinical trial for IDH mut glioma testing GLS inhibitor (NCT03528642)." (PMID 33681764, 2021). "We also found that under nutrient conditions that approximate the in vivo metabolic environment, glutaminase inhibition has only modest effects even in ENO1-deleted glioma cells, which are quite sensitive in “normal” media." (PMID 34172075, 2021). "Several studies have reported that a blockade of glutaminase activity results in the suppression of IDH mutant glioma and AML." (PMID 32825279, 2020). "Increased levels of GLS isoforms found in human GBM tissues make these proteins attractive targets for anti-glioma therapy." (PMID 32013066, 2020).
glioma (continued). "The IDH mutant gliomas (patient-derived glioma stem-like cells and human oligodendroglioma cell line grown in vitro and in xenografts) were also shown as being specifically sensitive to GLS inhibition by CB-839." (PMID 32013066, 2020). "It was shown that HOTAIR modulates GLS expression by functioning as a competing endogenous RNA (ceRNA) for miR-126-5p, since this miRNA directly targets GLS mRNA, increasing glioma glutamine metabolism." (PMID 32326003, 2020). "D-2HG also inhibits the branched-chain amino acid transaminase 1 (BCAT1) and 2 (BCAT2), which renders IDH1 mutant glioma cells dependent on glutaminase and increases their sensitivity to oxidative stress." (PMID 31450721, 2019). "A subset of leukemia cells with mutations in the metabolic enzymes isocitrate dehydrogenase 1 (IDH1) and 2 (IDH2), and IDH1-mutant glioma cells have been shown to be particularly sensitive to glutaminase inhibition." (PMID 27806325, 2016). "Thus, the prior identification of AC005229.4, LIPT2 and GLS as having a role in the advancement of gliomas and other types of cancer provides support for our findings." (PMID 39913607, 2025). "In gliomas, gene expression analysis confirmed a correlation between the expression of CRGs and genes involved in glutaminase activity, which also correlated with a poorer prognosis of glioma patients and with the extent of immune cell infiltration in the tumors." (PMID 39062119, 2024). "Inhibitors of additional metabolic enzymes in gliomas, such as glutaminase (GLS1) via CB-839, fatty acid synthase (FASN) via TVB-2640, isocitrate dehydrogenases (IDH) 1-2 via ivosidenib (AG-120) and vorasidenib (AG-881), and IDO-1 via indoximod (1-MT) and epacadostat (INCB024360)." (PMID 38292487, 2023). "Therefore, we believe that the cuproptosis-related glutaminase gene can be an important factor in determining the prognosis of glioma patients." (PMID 36158220, 2022). "At the same time, the expression of the glutaminase gene was positively correlated with the degree of immune cell infiltration and the expression of various immune cell markers, and thus affected the prognosis of glioma patients." (PMID 36158220, 2022). "SNAP25, a tumor suppressor inhibited carcinogenesis of glioma via limiting glutamate metabolism by regulating GLS expression, as well as inhibiting dendritic formation, which could be considered as a novel molecular therapeutic target for glioma." (PMID 34490096, 2021). "SNAP25 could regulate glutaminase (GLS)-mediated glutaminolysis, and GLS knockdown could rescue the anti-tumor effect of SNAP25 in glioma cells." (PMID 34490096, 2021). "We hypothesized that SNAP25 could regulate GLS-mediated glutamine metabolism to inhibit glioma progression." (PMID 34490096, 2021). "Hence, the link between GLS isoforms and neoplastic transformation seems supported by convincing evidence in human gliomas, lung and liver tumors." (PMID 32042057, 2020). "Since Gln can serve as a carbon source to produce 2HG in IDH1mut cancers, GLS inhibitors may provide therapeutic benefit in the treatment of these gliomas." (PMID 33101674, 2020). "In addition, several substrate utilisation capacities can be observed in these glioma cells (e.g. GLS and CPT1A protein expression levels are higher in glioma cells)." (PMID 31187466, 2020). "However, little is known about the contribution of the Gln/Glu pathway to 2HG formation and the metabolic consequences of targeting GLS in IDH1mut gliomas." (PMID 33101674, 2020). "In addition to the Warburg effect, several studies have demonstrated that inhibition of glutaminolysis by inhibiting GLS can suppress cancer growth, including gliomas." (PMID 27588472, 2016). "The proliferation, migration, and invasion assays proved that knockdown of GLS accelerated the proliferation, migration and invasion rate of glioma parental cells, and downregulation of GLS in SNAP25-overexpressesd glioma cells could rescue the tumor-suppressive function of SNAP25 in glioma cells." (PMID 34490096, 2021).
glioma (continued). "Therefore, inhibition of glutaminase slowed down the growth of IDH1-mutant glioma cells." (PMID 34356864, 2021). "Moreover, the glutaminase inhibitor JHU-083, a pro-drug that can penetrate the blood–brain barrier and is converted into 6-diazo-5-oxy-L-norleucin, caused a marked reduction in cell proliferation and downregulation of the mTOR pathway in animal models of IDH1-mutant gliomas." (PMID 39595047, 2024). "Glutaminase inhibitors thus exploit this defect and effectively decrease glutathione pools in IDH-mutant gliomas, increasing sensitivity to RT and oxidative stress." (PMID 39025958, 2024). "The expression of GLS (p < 0.001), LIPT1, FDX1, SLC31A1 (p < 0.01), DLST, CDKN2A, PDHA1, ATP7A, ATP7B, and NFE2L2 (p < 0.05) was different between glioma and adjacent tissues." (PMID 36936439, 2023). "Only GLS and ATP7B had low expression levels in glioma patients; however, others, including FDX1, LIPT1, DLD, and SLC31A1, were overexpressed." (PMID 37515314, 2023). "In this work, we studied, in more detail, the metabolic effects of inhibiting GLS activity by using CB-839 in several human glioma cell lines (T98G, LN229, and U87MG) with different Gln and/or GLS dependency." (PMID 36672480, 2023). "In particular, D-2HG can inhibit BCAT1 and BCAT2, inducing glioma cells dependent on glutaminase and more sensitive to oxidative stress compared to IDH wild-type glioma cells." (PMID 33923299, 2021). "Second, the marked change in glutathione and oxidative status following GLS silencing or GAB overexpression are a promising tool against cancer progression, including glioma cells." (PMID 33610185, 2021). "We confirmed that GLS acted as a metabolic target of SNAP25 and consequently decelerated glioma progression." (PMID 34490096, 2021). "In this study, actinomycin D was found to significantly downregulate the expression levels of several glioma metabolic enzymes, including HK2 and PKM2 from glycolysis, GLS from glutaminolysis and FASN from lipogenesis." (PMID 34063013, 2021). "Gene expression analysis detected GLS1 isoforms (KGA and glutaminase C [GAC]), using specific primer sets, and GLS2 mRNA in JHH520, TS603, BT142 glioma neurospheres and in JHH273 xenograft tumor." (PMID 33681764, 2021). "Specifically, our glioma cell lines overexpress ASNS among other Glu-utilizing enzymes which have the ability to generate Glu, bypassing the GLS reaction." (PMID 33101674, 2020). "MYC is known to regulate glutamine utilization and glutaminase protein expression, and mutant IDH gliomas are known to have an increased expression of MYC." (PMID 25376594, 2014). "GLS inhibitor telaglenastat has shown promising results in preclinical studies and is currently being investigated in a clinical trial for patients with IDH mutant gliomas in combination with radiation therapy and temozolomide." (PMID 40949165, 2025). "Glutamine-deprived glioma cells showed decreased proliferative activity, an effect replicated when liver-derived glutaminase, which is not expressed in glioma cells, is transfected in glioma cell lines." (PMID 39595047, 2024). "GLS inhibition by CB-839 induced a dose-dependent decrease in the cell proliferation of all the assayed GBM cell lines, as expected from previous results in several glioma cells." (PMID 36672480, 2023). "In addition, we provided further physiological evidence for a connection between glutaminolysis and lipogenesis by showing the molecular link between glutaminase (GLS) expression and SREBP-1 activation in human lung cancer and glioma tissues." (PMID 36009491, 2022). "Although some miRNAs have been shown to regulate GA expression in certain types of cancers, it is currently unknown whether similar miRNA mechanisms would contribute to GLS activation and GLS2 repression in gliomas." (PMID 33610185, 2021).